CTLA4 (cytotoxic T-lymphocyte associated protein 4)
Diseases named in the same sentence as CTLA4 in open-access papers (continued):
Sharing a sentence is not in itself a finding about the gene and the disease.
melanoma (continued). "Even though targeting CTLA-4 and PD-1 pathways with mAbs improved treatment outcomes for late-stage melanoma patients, we did not observe any therapeutic effect of these antibodies in our mouse model." (PMID 27160390, 2016). "Modulating both inhibitory and stimulatory immune pathways may also be a promising approach as dual CTLA-4 blockade and ICOS stimulation provides improved antitumor control against preclinical murine melanoma and prostate cancer." (PMID 27057463, 2016). "Pre-clinical melanoma models showed that tumors do not always respond to an anti-CTLA-4 mAb alone, while additive treatments with GM-CSF or activation of the T-cell co-stimulatory receptor 4-1BB are able to promote an anti-tumor response." (PMID 26500646, 2015). "An ongoing phase I study is exploring combination anti-CTLA-4 and CD40 agonist therapy in stage IV melanoma (NCT01103635), and another phase I/II trial assessing the safety and efficacy of CD40L gene therapy via a modified adenovirus vector is currently recruiting (NCT01455259)." (PMID 29546098, 2015). "The observation that immune response gene signatures may be associated with improved survival outcome is intriguing when considering novel immunotherapies, such as anti-CTLA4 and anti-PD1 antibodies in melanoma." (PMID 25909218, 2015). "In melanomas, CD8 and CD4 TILs display high expression of PD-1 and CTLA-4." (PMID 26175923, 2015). "A trial examining the effects of GITRL-expressing DCs (with or without DC expressing anti–CTLA-4) plus a DC tumor vaccine in patients with melanoma is also ongoing (NCT01216436)." (PMID 24855562, 2014). "Toxicity from TKI or mTOR inhibitors for RCC and from chemotherapy, BRAF inhibitors or anti-CTLA-4 antibodies for melanoma are low-grade but continuous and exert a negative impact on quality of life." (PMID 25245327, 2014). "Metastatic melanoma treatment has considerably progressed in the past five years with the introduction of targeted therapy (BRAF and MEK inhibitors) and immune checkpoint blockade (anti-CTLA4, anti-PD-1, and anti-PD-L1)." (PMID 25610709, 2014). "This indicates that human immunoglobulins do not compete with Ipilimumab bound to CTLA-4 expressed on melanoma cells for the binding with FcγRIIIA." (PMID 23634660, 2013). "Via blocking the CTLA-4 inhibitory signal, and allowing cytotoxic T lymphocytes (CTL) to destroy tumor cells, ipilimumab was approved in 2011 by FDA for the treatment of melanoma." (PMID 24015299, 2013). "The combination of CTLA-4 blockade and vaccination with B16 or SM1 cells, genetically modified to express GM-CSF, showed enhanced efficacy and tumor regression when administered in a B16 melanoma model and SM1 mammary carcinoma model, respectively." (PMID 24348481, 2013). "Immunomodulation with the anti-CTLA-4 monoclonal antibody ipilimumab has been shown to extend overall survival (OS) in previously treated and treatment-naive patients with unresectable stage III or IV melanoma." (PMID 24278787, 2013). "When CTLA-4/B7 interactions are blocked by injection of anti-CTLA-4 monoclonal antibody during cancer vaccination, therapeutic T-cell immunity against even poorly immunogenic tumours such as B16 melanoma can be eliminated." (PMID 22312406, 2012). "One patient with melanoma received CTLA4 antibody after radiation and did not experience any adverse side effects from SBRT." (PMID 21477295, 2011). "No polymorphisms of CTLA-4 defined by the SNPs studied were correlated with improved RFS, OS, or autoimmunity in this high-risk group of melanoma patients." (PMID 21044351, 2010). "These investigators concluded that administration of the CTLA4-blocking antibody ipilimumab to patients with melanoma neither depleted Treg nor downregulated their functional immune suppressive activity." (PMID 18452610, 2008).
melanoma (continued). "Our data confirm observations by others that administration of CTLA4-blocking antibodies to patients with melanoma does not result in the sustained expansion of circulating melanoma antigen-specific CD8+ T cells." (PMID 18452610, 2008). "Melanoma cells have been shown to express negative checkpoint regulators, such as PD-L1 and CTLA-4." (PMID 41463150, 2025). "Interestingly, though there was a slightly increased incidence of vasculitis and NMJ disorder complications in melanoma patients receiving both PD-1 and CTLA-4 inhibitor therapies, this difference was not statistically significant." (PMID 40351833, 2025). "While the advent of immunotherapy has brought new hope to patients with advanced melanoma, not all individuals respond to immune checkpoint inhibitors (ICIs) targeting PD-1/PD-L1 or CTLA-4, with primary or acquired resistance being a persistent obstacle in a subset of patients." (PMID 40599859, 2025). "In the CheckMate 067 trial, nivolumab monotherapy maintained a stable global health status in patients with advanced melanoma, with no significant deterioration over time compared with ipilimumab (CTLA-4 inhibitor), which has also been shown to maintain a stable HRQL in this population." (PMID 41463169, 2025). "For example, mice were engrafted with MC38 colon adenocarcinoma or B16-OVA melanoma cells, the tumor volumes of non-H.pylori-infected mice undergoing anti-CTLA-4 and/or PD-1 or anti-cancer vaccine treatments were significantly smaller than those of H.pylori-infected mice." (PMID 40308586, 2025). "Ipilimumab, a specific monoclonal antibody targeting CTLA-4, interacts with primary NK cells, IL-2-activated NK cells, and γδT cells via FcγRIIIA receptors, thereby triggering antibody-dependent cell-mediated cytotoxicity (ADCC) responses against CTLA-4-expressing melanoma cell lines and tissues." (PMID 40463500, 2025). "In addition, due to the lack of an indication for anti‐CTLA‐4 drugs in melanoma in China, along with other objective factors, there is a shortage of advanced melanoma patients undergoing combined immunotherapy in our study." (PMID 39968494, 2025). "Moreover, not only (increased) PD1- and CTLA4-expressing T-cells, but also PD1- and CTLA4-expressing (circulating) disseminated cancer cells were detected in patients with solid tumors (e.g., melanoma; lung, breast, and pancreatic cancer); (Hodgkin/Non-Hodgkin) lymphoma or leukemia." (PMID 41008794, 2025). "For the melanoma cohort, 78% of patients had a diagnosis of cutaneous melanoma with BRAF wild type status (BRAF is the most commonly altered genetic alteration in melanoma and used for treatment decisions), and most patients were treated with combination anti-PD-1 and anti-CTLA-4." (PMID 40217292, 2025). "In patients with melanoma, endogenous secretion of CXCL9 and CXCL10 positively correlates with improved prognosis and overall response by induction of CD8+ T-cell recruitment to the tumor site and correlates with improved response to anti–PD-1 and anti–CTLA-4 blockade in vitro." (PMID 39867570, 2025). "Additionally, in 2022, a non-CAR γδ T cell was developed via the inhibition of CTLA-4 and PD-1 on Vδ2 T cells using monoclonal antibodies to increase γδ T cell infiltration and killing of melanoma cells." (PMID 40148988, 2025). "This may also explain why tilsotolimod in combination with ipilimumab (anti–CTLA‐4) did not improve ORR or OS in a phase 3 trial in advanced PD‐1 blockade–resistant melanoma." (PMID 40753466, 2025). "Particularly, the triple combination of anti-PD-L1, anti-CTLA-4 and CSC-DC vaccine significantly eliminated ALDHhigh CSCs, which was accompanied by improved T cell expansion, suppressed TGF-β release, increased IFN-γ, and promoted CD8+ T cell response against melanoma CSCs." (PMID 41233805, 2025). "While CTLA‐4 expression in canine tumours has not been previously reported, several studies have shown its induction in neoplastic cells of human solid tumours, including melanoma." (PMID 39789732, 2025).
melanoma (continued). "To this end, we randomly assigned mice into 4 groups: 1, Control (no tumor, treated with ITC as vehicle control); 2, Melanoma + Veh (tumor treated with ITC); 3, Combi-ICI (no tumor, treated with anti-CTLA4 & anti-PD-1); 4, Melanoma + Combi ICI (tumor treated with anti-CTLA4 & anti-PD-1)." (PMID 40313772, 2025). "However, this area remains a significant focus of ongoing research, especially in the context of advanced melanoma that has not responded to standard immunotherapies, including anti-CTLA4 and anti-PD1 antibodies." (PMID 38474231, 2024). "Indeed, IFN-γ signaling is frequently down-regulated in melanoma and seems important for the response to anti-CTLA4 and anti-PD1 therapies but might play a dual role in melanoma or other types of cancers (pro- or anti-tumorigenic)." (PMID 38247871, 2024). "Melanoma (B16-OVA) burdened CD11c-Cre+Stat3f/f (Stat3Δ/Δ) mice, which are prone to autoinflammatory colitis, experienced a decrease in body weight and enhanced histological evidence of colitis following anti-CTLA-4 administration when compared to isotype control and Stat3+/+ groups." (PMID 39247203, 2024). "Additionally, the exploration of targeted therapies, focusing on IL-6 and CTLA4, as well as investigating the immune microenvironment in HCV-infected melanoma patients, could lay a solid foundation for future therapeutic strategies." (PMID 39336572, 2024). "Notably, melanoma patients with BRAF and NRAS mutations who have failed to respond optimally to agents like anti-PD-1 or anti-CTLA-4 antibodies have exhibited either partial response or long-stable disease (SD) after receiving TIL treatment." (PMID 38835341, 2024). "Consequently, targeting miRNA-155 or other factors involved in CTLA-4 regulation specifically in Treg cells, without affecting T cells, has the potential to enhance the effectiveness of immunotherapy in treating melanoma." (PMID 38462628, 2024). "Therefore, we asked if BQ could improve anticancer immunity in the B16F10 melanoma immunocompetent mouse model, which is typically refractory to dual ICB (i.e., anti-PD-1 plus anti-CTLA-4)." (PMID 38973593, 2024). "Therefore, we utilized melanoma immunotherapy studies, in which clinical and gene expression data were obtained from published studies on melanoma patients receiving anti-PD-1 monotherapy, anti-CTLA-4 monotherapy or anti-PD-1/anti-CTLA-4 combined therapy." (PMID 38835778, 2024). "Our ICBcircSig score model is a highly robust predictor of the efficacy of immunotherapy in patients with melanoma, irrespective of whether they are undergoing anti-PD-1 treatment alone or combined anti-CTLA-4 and anti-PD-1 treatment." (PMID 37137884, 2023). "Furthermore, we show that melanoma secretome induces downregulation of CTLA4 through miR-155 expression in Treg cells without decreasing their FOXP3 expression." (PMID 37197667, 2023). "Tregs in TME can reduce the content of IL-2 in TME and promote the expression of CTLA4 by producing immunosuppressive components such as TGF-β, IL-10 and extracellular adenosine, thus inhibiting the physiological function of CD8+ T cells and favouring immune evasion of melanoma cells." (PMID 37221594, 2023). "Ipilimumab is the first, and only Food and Drug Administration (FDA) approved CTLA-4 inhibitor, which was initially approved in 2011 based on the pivotal Phase 3 MDX010-020 trial that demonstrated an OS advantage in patients with unresectable, previously treated, late-stage melanoma." (PMID 38067319, 2023). "Moreover, this anti-CTLA-4 nanobody could increase the anti-tumor activities of cytotoxic T cells and prolong the survival of NOD/SCID mice bearing melanoma cells." (PMID 36761751, 2023).
melanoma (continued). "For instance, in the mouse B16 melanoma model, phosphofructokinase 2/ fructose-2, 6-bisphosphatase 3 (PFKFB3) stimulates glycolytic activity and lactic acid generation in tumor cells, while PFK-158, its inhibitor, enhances the therapeutic response of antibodies against CTLA-4." (PMID 36677919, 2023). "Furthermore, the data from the AUS cohort indicate that blood CTLA4 levels determine the melanoma patient prognosis independent of age and sex, specifically in the AUS cohort." (PMID 37197667, 2023). "Furthermore, the data from the AUS cohort indicate that blood CTLA4 levels determine the melanoma patient prognosis independent of age and sex." (PMID 37197667, 2023). "However, its efficacy, especially in combination with anti-PD-1 ± anti-CTLA-4, in murine melanoma is not known." (PMID 36920329, 2023). "Even while ICIs greatly boosted melanoma patients' chances of survival, 40–65 percent of those taking PD-1 inhibitors and more than 70 percent of those taking CTLA-4 inhibitors did not exhibit positive response, primarily because of the emergence of resistance." (PMID 37038154, 2023). "Notably, patients with melanoma subjected to treatment with the anti-CTLA-4 antibody, ipilimumab, exhibited a marked reduction in granulocyte levels, suggesting a potential dearth of synergistic interaction between CTLA4 and neutrophils." (PMID 37679744, 2023). "Similarly, mouse melanoma lacking Pbrm1, another subunit of the SWI/SNF complex, displayed increased susceptibility to combined PD-1 and CTLA-4 blockade than control tumors." (PMID 37614504, 2023). "In a preclinical melanoma model, tumor-intrinsic β-catenin activation was shown to impair the infiltration of T cells and CD103+ DCs, which is related to reduced CCL4 secretion from tumors and leads to therapeutic resistance to the combined PD-1 and CTLA-4 blockade." (PMID 37614504, 2023). "Our findings suggest that targeting miR-155 or other factors involved in regulating CTLA4 expression in Treg cells, without affecting T cells, could be a potential strategy to improve the efficacy of immunotherapy in melanoma." (PMID 37197667, 2023). "In addition, viral mimicry sensitizes melanoma to anti-PD1 and anti-CTLA4 therapy." (PMID 36755342, 2023). "However, NUDCD1 did possess significant mutation differences between responders and non-responders for anti-CTLA-4 (ipilimumab) therapy for melanoma." (PMID 37338527, 2023). "In addition to monotherapy with ipilimumab, this CTLA-4 inhibitor combined nivolumab led to longer progression-free survival (PFS) and a higher objective response rate (ORR) in a phase 3 trial in patients with advanced melanoma (NCT01844505)." (PMID 34980128, 2022). "A combination of anti-PD1 and anti-CTLA4 blockade therapy with nivolumab and ipilimumab was found to have a higher ORR (57%) than monotherapy with ipilimumab (19%) and nivolumab (44%) in a phase 3 study in patients with untreated melanoma, suggesting increased efficacy in combination." (PMID 36429020, 2022). "In poorly immunogenic tumor models, the use of CTLA-4-blocking antibodies alone was not sufficient to improve patient survival/shrink tumor mass, but in combination with a DC vaccine, patients with melanoma had increased TILs, specific T cell responses, and clinical benefit in a pre-clinical trial." (PMID 35806328, 2022). "Our data from n = 106 stage III/IV melanoma patients who received combinational ICB therapy with anti-PD-1 and anti-CTLA4 identifies age, but not underlying herpes virus immunity or peripheral TEM subsets as the major variable associated with the risk for immune-checkpoint associated hepatitis." (PMID 36503532, 2022). "Among them, immune checkpoint blocking therapy, represented by PD-1/PD-L1 inhibitors (nivolumab) and CTLA-4 inhibitors (ipilimumab), has shown encouraging therapeutic effects in the treatment of various malignant tumors, such as non-small cell lung cancer (NSCLC) and melanoma." (PMID 36123348, 2022).
melanoma (continued). "In this real-world study of ICI use in the era of adjuvant therapy for melanoma, we found that risk of all-cause AKI increases with more advanced cancer stage, yet the risk of ICI-associated AKI is only driven by the use of anti-CTLA-4/PD-1 combination therapy and not cancer stage." (PMID 36531890, 2022). "Besides immunotherapy with CTLA4 and PD1 inhibitors, we have recently reported the efficacy of targeting the inducible T-cell co-stimulator (ICOS)/ICOS ligand (ICOS-L) dyad in mouse models of melanoma." (PMID 36500861, 2022). "In the sub-study 02A of the KEYMAKER-U02, 200 patients with PD-1 refractory melanoma are randomized to receive vibostolimab (MK-7684), a TIGIT blocking humanized IgG1 monoclonal antibody, or lenvatinib with pembrolizumab and quavonlimab (anti-CTLA-4) (NCT04305041)." (PMID 35053435, 2022). "Indeed, immune checkpoint blockade (ICB) therapy targeting PD-1 and CTLA-4 pathways, often in combination as dual immune checkpoint blockade (DICB) therapy, has revolutionized the treatments of cancers including melanoma, non-small cell lung cancer, and bladder cancer." (PMID 35514996, 2022). "Moreover, a cluster of cancer-germline antigens, located in chromosome Xq28, predicted resistance to CTLA-4 blockade (but not to PD-1 blockade) in melanoma patients." (PMID 35628196, 2022). "For example, a recently published phase 2–3 study combining anti-LAG3 and anti-PD1 antibodies in melanoma patients reported 7/355 (2%) acute renal dysfunction, whereas this adverse events was not described in the original studies describing anti-CTLA4/anti-PD1 combination." (PMID 36552755, 2022). "Given TRM widely express CTLA-4, PD-1 and LAG-3, which are inhibited by immune checkpoint inhibitors such as ipilimumab, nivolumab, pembrolizumab and relatlimab provides a strong biological rationale this CD8 subset is critical in facilitating anti-tumor responses in melanoma." (PMID 36466880, 2022). "It has been reported that CTLA-4 siRNA-loaded nanoparticles could increase the number of CD8+ T cells, decrease the ratio of CD4+ FOXP3+ Tregs and effectively inhibited tumor growth in mice with melanoma." (PMID 34875483, 2022). "In addition, we found that patients with thyroid dysfunction and skin toxicity had a better prognosis, which is also consistent with previous meta-analysis for non-small cell lung cancer (NSCLC), melanoma and renal cell carcinoma (RCC) treated with anti-PD-1 antibody or anti-CTLA-4 antibody." (PMID 36335320, 2022). "Although anti-CTLA-4 alpaca heavy chain-only Fab could sufficiently block CD80/86-CTLA-4 interactions and localize in B16-F10 melanoma tumors, it did not reduce tumor burden or deplete intra-tumoral Tregs." (PMID 35326731, 2022). "Immune checkpoint inhibitors (ICIs), such as anti-programmed cell death 1 (PD1) antibodies (Abs) and anti-cytotoxic T-lymphocyte associated protein 4 (CTLA4) Abs, have been widely administered for not only advanced melanoma, but also various non-melanoma skin cancers." (PMID 35409404, 2022). "Furthermore, these studies also identify a unique anti-tumor resistance in Mertk-/- V1 mice against anti-CTLA-4 and anti-PD-1 refractory YUMM1.7 melanoma as well as against GL261 brain tumors, the molecular basis of which remains unknown." (PMID 35969037, 2022). "Given CTLA-4 complex mechanism on the immune system, inhibiting CTLA-4 action might enhance immunosurveillance, and first antibody against CTLA-4, ipilimumab, which can bind both mCTLA-4 and sCTLA-4, was approved in 2011 for the treatment of melanoma." (PMID 34006227, 2021). "Similarly, the first report on CTLA-4 blockade (negative regulator of T-cell activation) in anti-tumor immunity was demonstrated in 1996 and the first clinical report of CTLA-4 against melanoma in 2003." (PMID 34571899, 2021).